PSMB9 (proteasome 20S subunit beta 9)
Diseases named in the same sentence as PSMB9 in open-access papers (continued):
Sharing a sentence is not in itself a finding about the gene and the disease.
idiopathic inflammatory myopathies (1 paper, 2022). "Previous research reported that PSMB8, PSMB9 and PSMB10 expressed at significantly abundant levels in dendritic cells, monocytes, and CD8+ T-cells in idiopathic inflammatory myopathies, which correlated highest with STAT1, IRF1 and IFN-γ expression." (PMID 35933405, 2022).
inflammatory bowel disease (1 paper, 2019). A spectrum of small and large bowel inflammatory diseases of unknown etiology. "PSMB8 and PSMB9 constitute interferon-inducible immunoproteasome mediating intestinal NF-κB activation in inflammatory bowel diseases (IBD)." (PMID 31888082, 2019).
lumbar disc herniation (1 paper, 2023). "Immunohistochemical staining of PSMB9, STAT1, and TAP1 was performed in 5 patients with spinal tuberculosis and 5 patients with lumbar disc herniation." (PMID 37340462, 2023).
Parkinson disease (1 paper, 2023). A progressive degenerative disorder of the central nervous system characterized by loss of dopamine producing neurons in the substantia nigra and the presence of Lewy bodies in the substantia nigra and locus coeruleus. "A case-control study conducted to assess correlations between several genes and Parkinson's disease in a Chinese population showed that women carrying the PSMB9 rs17587 G/G genotype seemed to have an increased risk for Parkinson's disease, whereas men carrying the same genotype did not." (PMID 36937130, 2023).
renal carcinoma (1 paper, 2024). A carcinoma arising from the epithelium of the renal parenchyma or the renal pelvis. "Along these lines, upregulation of PSMB9 is an unfavorable prognostic marker in renal cancer." (PMID 38774235, 2024).
rheumatoid arthritis (1 paper, 2023). A chronic, systemic autoimmune disorder characterized by inflammation in the synovial membranes and articular surfaces. "In addition, the three genes (PSMB9, CD74, and HLA-F) were validated in other rheumatologic disorders including systemic lupus erythema (SLE) and rheumatoid arthritis (RA)." (PMID 37153570, 2023).
schizophrenia (1 paper, 2025). A major psychotic disorder characterized by abnormalities in the perception or expression of reality. "The microglial H-MAGMA-risk genes BAG6, NEU1, PRRC2A, PSMB8, PSMB8-AS1 and PSMB9 were associated with MS, ALS and schizophrenia." (PMID 40202986, 2025).
Sepsis (1 paper, 2025). Sepsis is defined as life-threatening organ dysfunction caused by a dysregulated host response to infection. "Additionally, a study by Ma Carmela P Dela Cruz demonstrated that PSMB9 is highly expressed in surviving sepsis patients, supporting its accuracy as a prognostic biomarker." (PMID 41332909, 2025).
tuberculosis (1 paper, 2023). A chronic, recurrent infection caused by the bacterium Mycobacterium tuberculosis. "In this study, we found that cyclosporin can upregulate the expression of PSMB9 and STAT1, which may be one of the mechanisms of cyclosporin-induced increased risk of activation of tuberculosis disease." (PMID 37340462, 2023).
urothelial bladder carcinoma (1 paper, 2023). "Because recent evidence has demonstrated an immunological role for proteasomes in various malignancies, including urothelial bladder carcinoma (UBC), we evaluated single nucleotide polymorphisms (SNPs) in PSMB9 and PSMB8." (PMID 36937130, 2023).
urothelial carcinoma (1 paper, 2022). A malignant neoplasm derived from the transitional epithelium of the urinary tract (urinary bladder, ureter, urethra, or renal pelvis). "Our previous studies found a co-expression network associated with CD8+ T lymphocyte invasion in urothelial carcinoma, which contains PSMB8, PSMB9, PSMB10, PSME2, IRF1 and other genes." (PMID 36700205, 2022).
tumor (130 papers, 2007 to 2026). "Our analyses revealed that PSMB9 is aberrantly expressed in most malignancies, with context-dependent associations with tumor stage and patient survival." (PMID 41020834, 2025). "Our analyses revealed that PSMB9 expression was significantly positively correlated with TMB in the majority of tumor types, with particularly strong associations observed in USC, SARC, COAD, COADREAD, KIPAN, and BRCA." (PMID 41020834, 2025). "In our subsequent research, we will also conduct further investigations into the specific molecular mechanisms by which tumor PSMB9 deficiency interferes with CAR T cell efficacy." (PMID 41020834, 2025). "When looking at the OS and metastases, significant associations were found for PSMB8-expressing tumor cells and OS, as well as PSMB9-expressing tumor cells and brain metastasis." (PMID 36746983, 2023). "For macrophages, high PSMB9 expression within the tumor was linked to increased phagocytosis, which could suggest enhanced tumor clearance and subsequent presentation of cancer antigens." (PMID 40698074, 2025). "Furthermore, CRISPR/Cas9 screening identified PSMB9 loss as a novel mechanism of resistance to CD19 CAR T cell therapy, with PSMB9-deficient tumor cells exhibiting a survival advantage under CAR-T pressure, supported by trends in clinical CAR-T outcomes." (PMID 41020834, 2025). "We further investigated the association between PSMB9 expression and tumor stage by integrating TCGA pan-cancer data, with results revealing significant stage-dependent differences in PSMB9 expression across multiple malignancies, exhibiting cancer-specific regulatory directions." (PMID 41020834, 2025). "Taken together, PSMB9 could be associated with the sensitivity of tumor cells to CAR-T cell therapy, suggesting that the loss of PSMB9 might be a novel molecular mechanism for tumor cells to escape from CAR-T cells." (PMID 41020834, 2025). "Moreover, PARP9 expression positively correlates with metastasis of axillary lymph node and is negatively associated with ER expression, as well as PSMB8 and PSMB9 and immunoproteasomes, which induce tumor angiogenesis via VEGF-A and are overexpressed in most cancers, including BC." (PMID 36766731, 2023). "Here we investigated the context-dependent functions of PSMB9 by integrating multi-omics data from The Cancer Genome Atlas, Genotype-Tissue Expression database, Human Protein Atlas, Tumor Immunotherapy Gene Expression Resource, and multiple other databases." (PMID 41020834, 2025). "In this study, we systematically characterized PSMB9 across human cancers, uncovering its dysregulated expression, prognostic significance, and critical involvement in shaping the tumor immune landscape." (PMID 41020834, 2025). "Despite limitations in cohort heterogeneity, this study positions PSMB9 as a pivotal orchestrator of tumor immune landscapes, highlighting its potential as a biomarker and therapeutic target to advance precision immunotherapy." (PMID 41020834, 2025). "CD3E and PSMB9 were involved in the processes of antigen processing and presentation, and further enhances the anti-tumor immunity mediated by T lymphocytes." (PMID 40424327, 2025). "Another aspect of PSMB9 biology uncovered in this study is its complex genetic and epigenetic regulation, coupled with its inverse correlation with tumor stemness, which sheds light on its role in tumorigenesis beyond immune modulation." (PMID 41020834, 2025). "Taken together, these findings underscore a multifaceted role of PSMB9 in modulating responses to immunotherapy, with its expression levels exhibiting predictive value across diverse tumor types and therapeutic approaches." (PMID 41020834, 2025). "In order to further elucidate the characteristics of PSMB9 and its role in tumorigenesis and progression, we analyzed the alteration profiles of PSMB9, its RNA modification features, and its potential regulatory role in tumor stemness." (PMID 41020834, 2025).
tumor (continued). "Here, we established this pan-cancer analysis to systematically elucidate the role of PSMB9 in orchestrating tumor immune processes and its potential as a novel predictive biomarker for T cell-based immunotherapy responses in diverse malignancies." (PMID 41020834, 2025). "The analysis revealed that, in the majority of tumors, PSMB9 expression was significantly negatively correlated with tumor stemness." (PMID 41020834, 2025). "PSMB9 expression also showed a consistently positive relation to dendric cells and macrophages in most tumor types." (PMID 41020834, 2025). "To further clarify the expression level of PSMB9 in tumors, we first examined the expression level of PSMB9 in different tumor cell lines." (PMID 41020834, 2025). "Significantly positive correlation between PSMB9 expression and immune cell infiltration score was observed in 36 tumor types." (PMID 41020834, 2025). "Guide RNAs were employed to delete B2m, Jak1, or Psmb9 genes in ICB-responsive EMT6 murine tumor cells." (PMID 38427670, 2024). "As expected, the benefits of higher PSMB8- and PSMB9-positive tumor cells content were augmented when considering high-grade cancers only." (PMID 36746983, 2023). "The PSMB9 expression level in tumor tissues is much higher than in para-carcinoma tissue, suggesting that the expression of PSMB9 is highly correlated with LGG and affects various pathways in a subtle and complex way." (PMID 35928883, 2022). "The genes upregulated in MΦ subtypes from tumours treated with topical caerin gel including Stat2, Isg15, Tap1, Psmb9, and Parp9, were more highly expressed in the CCI than CCII MΦs." (PMID 36497272, 2022). "This indicates that different types of tumors contain different tumor environments, resulting in different functions of PSMB9 involved." (PMID 35928883, 2022). "Our research mainly analyzed the relationship between PSMB9 gene expression and characteristics among tumor samples through bioinformatics." (PMID 35928883, 2022). "PSMB9 transcript abundance independently predicted overall survival (OS) in 12 tumor contexts." (PMID 41020834, 2025). "Moreover, how PSMB9 influences the immune landscape within various tumor types remains insufficiently elucidated and warrants further molecular and immunological investigations." (PMID 41020834, 2025). "PSMB9 functions as IFN-γ-sensitive tumor suppressor and biomarker." (PMID 41293269, 2025). "Our study uncovers PSMB9 as a previously unrecognized critical regulator of the tumor immune landscape in a pan-cancer scope, whose expression orchestrates key immune processes within the tumor microenvironment and serves as a potent biomarker for patient prognosis." (PMID 41020834, 2025). "Tumor prognosis could be influenced by a variety of factors, and this seemingly paradoxical result highlights the complexity of the tumor immune microenvironment and the regulatory functions of PSMB9." (PMID 41020834, 2025). "PSMB9 was also broadly and negatively correlated with tumor stemness indices." (PMID 41020834, 2025). "Collectively, these results provided evidence that PSMB9 could play a pivotal role in cancer immune responses, prompting us to further investigate its function within the tumor microenvironment (TME)." (PMID 41020834, 2025). "Immunoproteasome genes are known to be mainly expressed by immune cells, meaning that expression of PSMB8 and PSMB9 genes in tumor samples could be driven by infiltrating immune cells." (PMID 39796785, 2025). "Tumor mutational burden (TMB) and microsatellite instability (MSI) are established critical biomarkers for ICI response; thus, we further explored the correlation between PSMB9 expression and these genomic features across multiple cancer types." (PMID 41020834, 2025). "Our report suggests that PSMB9 could play a crucial role in tumor immunogenicity and immunotherapy responsiveness across a variety of cancer types." (PMID 41020834, 2025).
tumor (continued). "In most other tumor types, the alteration rate of PSMB9 was less than 4%." (PMID 41020834, 2025). "To systematically dissect the differential expression patterns of PSMB9 between diverse tumor tissues and their matched normal counterparts, we integrated data from the TCGA and GTEx databases and analyzed PSMB9 expression in multiple cancer types and their corresponding normal tissues." (PMID 41020834, 2025). "PSMB9 plays a crucial role in antigen processing and presentation; however, its comprehensive role in orchestrating a tumor-immune landscape and regulating the anti-tumor immune responses remains unexplored." (PMID 41020834, 2025). "Increased immunogenic antigens resulting from higher PSMB9 expression could explain the significantly enriched tumor-infiltrated immune cells, represented by CD8+ T cells, which play a central role in antitumor activity in the TME." (PMID 41020834, 2025). "This widespread correlation suggests that PSMB9 may exert a significant role in antigen presentation, cytokine/chemokine signaling cascades, and immune checkpoint pathways during anti-tumor immune responses." (PMID 41020834, 2025). "Similarly, the expression of genes related to antigen processing and presentation such as Tap1, Tap2, B2m, and Psmb9, was also upregulated in tumors from hsBCL9z96-treated CT26 tumor-bearing mice and MC38 tumor-bearing Bcl9/Bcl9l deficiency mice." (PMID 38811552, 2024). "As for the key gene PSMB9, its anti-tumor effects had also been confirmed in some studies." (PMID 39252305, 2024). "Therefore, we also investigated the requirement for Psmb9 in regulating the growth of FAK-/- tumours." (PMID 36977556, 2023). "Tumor cells demonstrated enriched expression of the proteasome and immunoproteasome subunits Psmb8 and Psmb9 and major histocompatibility complex class I (MHC I) genes H2-K1, H2-D1, and B2m, consistent with upregulation of antigen processing and presentation machinery." (PMID 37041154, 2023). "It is deduced that PSMB9 protein may participate in the presentation of antigen proteins to reduce the immune escape of tumor cells, so it has great potential for immunotherapy." (PMID 35928883, 2022). "In the HPA data, compared with normal tissues, DHRS13, PLEKHH1were expressed at medium to high levels in tumor tissues, while the expression of PSMB9, and LRRN2 was significantly up-regulated in OC samples, and AMMECR1, KIAA0100 slightly downregulated in OC samples." (PMID 36307842, 2022). "Then, we conducted a difference test and linear regression analysis and found that there were significant differences in each indicator between the high and low expression groups, indicating that PSMB9 plays a role in tumor immunity and has stable prognostic ability in LGG patients." (PMID 35928883, 2022). "It shows that PSMB9 has the potential to be used as an immunotherapy target for tumor treatment." (PMID 35928883, 2022). "In the present study, similar to PSMB8, up-regulated PSMB9 transcriptional levels and higher PSMB9 encoding protein levels were found in ccRCC tissues compared to normal tissues, and PSMB9 mRNA expression was significantly related with patients' individual cancer stages and tumor grades." (PMID 35693739, 2022). "Therefore, the expression level of PSMB9 was increased in almost tumor tissues, and the higher the level, the more the expression." (PMID 35928883, 2022). "PSMB8 and PSMB9 overexpression was found to highly associate with CD4+ and CD8+ T-cell infiltration, regulatory T-cells, NK cells and M1-macrophages, in agreement with a role for IP subunit overexpression in enhancing the immune response in the tumor." (PMID 32060274, 2020).
tumor (continued). "This fact shows that PSMB9 functions differently in the different tumors, which matched the previous conclusion, and the consequence is the result of co-regulation by various components of the tumor microenvironment, but its ability as a prognostic marker in tumors is well established." (PMID 35928883, 2022). "Therefore, overexpression of PSMB6 might promote tumor growth through immunosuppression induced by the insufficiency of PSMB9." (PMID 35693739, 2022). "Also, it was shown that PSMB9 expression is absent in human uLMS but present in LM suggesting PSMB9 is a potential diagnostic biomarker and tumor suppressor for uLMS." (PMID 36291793, 2022). "In addition a set of 15 proteins that participate in the antitumor immune response such as the tumor suppressors PSMB9, ERAP1 and TAP1 or the interferon-stimulated genes IFIT1 and MX1 were found down-regulated in CUL4A-overexpresing cells and up-regulated in CUL4A-silencing models." (PMID 24870930, 2014). "PSMB9 displayed strong correlations with classical inhibitory molecules such as LAG3, PDCD1, CTLA4, TIGIT, HAVCR2, SLAMF7, and PD-L1 across nearly all tumor types." (PMID 41020834, 2025). "The PD-1 expression scores of tumour cells and immune cells in patients with high expression levels of PSMB8, PSMB9, and PSMB10 were greater than low expression samples." (PMID 36700205, 2022). "The IFN-gamma inducible genes (PSMB8/β5i, PSMB9/β1i, PSMB10/β2i), together with their chaperones have command of the tumor vulnerability to antigen-dependent killer cells." (PMID 34650125, 2021). "PSMB8, PSMB9, PSMB10, PSME2, TAP1, and IRF1 promote CD8+ T cell infiltration by enhancing MHC class I tumor antigen processing." (PMID 33330025, 2020). "Additionally, genes involved in the cellular response to stress were commonly upregulated in tumor C1 and C2 NK cells (HSP90AA1, HSPA1B, HSPH1, DNAJB1, PSMB9, CSTP1)." (PMID 41082397, 2026). "Interestingly, the 3 main immunoproteasome genes, PSMB8, PSMB9, and PSMB10, which digest cellular protein to antigenic peptides for antigen presentation, were also upregulated by VC in the WT tumor cells, as indicated by PSMB8 and others." (PMID 39388288, 2024). "Our data show a clear correlation between high ImP expression and better outcomes, most notably for TNBC patients and when tumor cells rather than stromal or immune cells express PSMB8 or PSMB9." (PMID 36746983, 2023). "Psmb9 depletion did not rescue FAK-/- tumour growth, implying that an intermediate proteasome containing Psmb8 is sufficient to restrain FAK-/- tumour growth." (PMID 36977556, 2023). "Although we did not analyze the overall level of protein expression in our cohort, it is possible that the number of cells expressing PSMB8 or PSMB9, but not the overall level of expression throughout the sample, increases with tumor grade." (PMID 36746983, 2023). "As such, some tumors contained high amounts of PSMB8+ CK8-18+ (tumor) cells, while some others were completely negative and the same phenotypes were observed for PSMB9." (PMID 36746983, 2023). "Also, PSMB9 is directly regulated by anti-oncogenic IRF1, a well-known gene with suppressor tumor activity." (PMID 36291793, 2022). "Eight co-expressed genes (PSMB8, PSMB9, PSMB10, PSME2, TAP1, IRF1, FBOX6, ETV7) were identified as CD8+ T cell-related genes that promoted infiltration of CD8+ T cells, and were enriched in the MHC class I tumor antigen presentation process." (PMID 33330025, 2020). "In the analysis of gene expression in whole proteasomes including PSMB5 (β5), PSMB8 (iβ5), PSMB7 (β2), PSMB10 (iβ2), PSMB6 (β1), and PSMB9 (iβ1), these genes alternated or showed only slight in their expression following silencing of PSMB5 or PSMB7 in three tumor cells." (PMID 29515784, 2018). "Notably, the consistent negative correlation between PSMB9 expression and tumor stemness indices across most tumors suggests a previously unrecognized role in suppressing stem cell-like properties." (PMID 41020834, 2025).
tumor (continued). "However, we found a strong correlation between the numbers of PSMB8 + and PSMB9 + cells, as well as between PSMB8 + and PSMB9 + tumor cells, which would suggest that using only one or the other could potentially be sufficient." (PMID 36746983, 2023). "This is the first report of the predictive role of PSMB9 in CAR-T therapy, suggesting that the lack of PSMB9 in tumor cells could possibly lead to acquired CAR-T cell resistance." (PMID 41020834, 2025).